STAT2 (signal transducer and activator of transcription 2)
Diseases named in the same sentence as STAT2 in open-access papers (continued):
Sharing a sentence is not in itself a finding about the gene and the disease.
tumor (continued). "In this regard, some critical transcription factor genes involved in tumor immunity, such as STAT1 and STAT2, were observed to have relatively high similarities with other genes." (PMID 34980132, 2022). "We further analyzed the tumor-upregulated target proteins of STAT1 and STAT2, and found these target proteins were mainly enriched in interferon gamma signaling, and response to immune." (PMID 35440542, 2022). "The anti-tumor immune response is dominated by two of these factors, STAT1 and STAT2, which act by inducing type I and type II interferons (IFN)." (PMID 35330716, 2022). "The downregulation of IRF9 and VCAN expression was conserved until tumor excision, STAT1, and CDKN1A expression showed decreased tendency and STAT2, and PCNA expression were significantly reduced in the IRF9-knockdown group." (PMID 33430083, 2021). "The results showed that the expression of STAT1, STAT2, STAT3, STAT5A, and STAT6 increased with increasing tumor grades." (PMID 34276757, 2021). "Type I and II interferons impinge upon tumor physiology by both affecting tumor cell proliferation and activating innate and adaptive anti-tumor immune responses through STAT1 and STAT2 activation." (PMID 34830776, 2021). "TB11-Fhit-transfected tumor cells showed a significant increase in the expression of IRF-1, Jak1, Ptpsh1, Stat1, Stat2, and Stat3 genes." (PMID 32545680, 2020). "In summary, we point out the role of IFNβ activated Stat1/Stat2/IRF9 signalling in cancer invasion plasticity, aside from its known role as a tumour suppressor." (PMID 32872349, 2020). "Conversely, restoring IFN-β expression in OSM-expressing TNBC cells restored the expression of select ISGs (including STAT1, STAT2, IRF9, SOCS1, MX1, and OAS1 and reduced tumor sphere formation and tumor-initiating capacity." (PMID 31036052, 2019). "Accordingly, we observed a significant increase in STAT1 and STAT2 signaling in survivin-specific T cells upon coculture with CCR9lo MCF7 cells, suggesting that anti-tumor type-1 immune response is impeded by tumor-specific CCR9 (Fig5D and E)." (PMID 25691366, 2015). "Nonetheless, the overarching pattern remained consistent: loss of STAT2 suppressed cell proliferation and tumor growth, whereas loss of IFNAR1 did not, underscoring their divergent roles in tumor biology." (PMID 41440237, 2025). "In this study, we found that p-STAT1 and p-STAT2, the key transducers of IFN-I signaling, can also be transferred from tumor cells to macrophages via secretory autophagy, thereby realizing the transmission and spread of IFN-I signaling between tumor cells and macrophages." (PMID 41321309, 2025). "The upregulation of LRP1B, RGS5, STAT2, and HLA-A in SDR42E1-depleted cells suggests enhanced apoptotic singling, tumor-immune crosstalk, and immune recognition—aligning with vitamin D’s immunomodulatory roles and potentially increasing chemotherapy sensitivity." (PMID 40756515, 2025). "STAT1/ STAT2 has a large number of target genes, including NO, BCL-2, p21, and CCND1, which all participate in pro-apoptotic and cell-cycle regulation, and act as tumor suppressors in various cancers." (PMID 38191598, 2024). "SCRIPro could accurately predicts well-known master regulators including SPI1, IRF1, FLI1, and STAT2 for mono/macrophages, GATA3, RUNX3, SMARCA4, JUND, and MYB for T-cells, PAX5, BCL2, and IRF4 for B and tumor B-cells." (PMID 39024032, 2024). "We can speculate that post-translational mechanisms may impact the maturation of RNA into protein in the metastatic tissue of responder patients, resulting in the modulation of tumor resistance pathways involving FADD and STAT2." (PMID 39273294, 2024). "In contrast, STAT2-sustained late IFN-I signaling promotes the expression of pro-inflammatory mediators and genes involved in chemoresistance and immunosuppression that confer tumor cell survival and disease progression." (PMID 38611065, 2024).
tumor (continued). "The average expression values of STAT1 (p < 0.001), STAT2 (p < 0.001), STAT3 (p < 0.001), STAT4 (p < 0.001), STAT5A (p < 0.001), STAT5B (p < 0.001), and STAT6 (p < 0.001) among immune subtypes C1-C6 in all tumor types were identified to have notable differences." (PMID 36968603, 2023). "Similarly, in vivo results show that the overexpression of IRF9 or STAT2 delays vemurafenib-induced tumor regression, whereas knockdown of IRF9 or STAT2 potentiates tumor growth inhibition." (PMID 36674798, 2023). "Interestingly, we found that IRF1, STAT1, STAT2, and STAT3 were all significantly downregulated in Scissor+ tumor cells compared to Scissor− and background tumor cells." (PMID 37021816, 2023). "STATs including STAT1–6 may exacerbate cell growth and cancer development (STAT3 and STAT5) and regulate the anti-tumor immune responses for tumor control (STAT1 and STAT2)." (PMID 38094755, 2023). "In contrast, the Oncotag treatment resulted in sustained downregulation of the pro-oncogenic molecules such as PDGFRβ, eNOS, PLC-γ1, JNK, p38α, Fgr, transcription factors STAT2, STAT5, and anti-apoptosis factor HSP27 and, probably, in long-term decrease in tumor aggressiveness." (PMID 37854069, 2023). "Likewise, the differences in the expression levels of STAT2, STAT3, STAT4, STAT5A, STAT5B, and STAT6 between normal and tumor tissues were also displayed." (PMID 36968603, 2023). "Thus, higher the expression of STAT1, STAT2, STAT3, STAT4, STAT5A, and STAT5B, the lower the tumor purity." (PMID 36968603, 2023). "Consequently, we deduced that high expression of STAT1, STAT2, STAT4, and STAT5A indicated low BRCA tumor purity." (PMID 36968603, 2023). "Hence, we proposed that higher STAT1, STAT2, and STAT4 expression suggested less tumor stemness characteristics." (PMID 36968603, 2023). "However, STAT3 and STAT5 have been studied more thoroughly, while the role of STAT1, STAT2, STAT4, and STAT6 in tumor development has been studied less thoroughly." (PMID 35244291, 2022). "The tumor suppressor function of CXCL10 and STAT2 is supported by several lines of evidence." (PMID 35207629, 2022). "STAT2, STAT4 and STAT6 appear to have more limited roles in tumor biology." (PMID 35163491, 2022). "Unlike wild-type mice, interferon-β treatment neither attracts CD4+ and CD8+ T cells to tumor sites nor suppresses tumor growth in Stat2-knockout mice." (PMID 35207629, 2022). "While STAT2 expression was found to be diminished among all cultured patient samples, STAT1 overexpression was maintained in Patient 1 cell culture, and similar trends of STAT1 expression were observed for the other selected tumor lines." (PMID 34943910, 2021). "In addition, both the FFPE and fresh frozen tumor analysis revealed overexpression of STAT1 and STAT2, even though two different platforms and two separate reference compendia have been used in the analyses." (PMID 34943910, 2021). "The mRNA levels of TGM2, USP18, DDX58, PARP9, STAT1 and STAT2 were not significantly different between ER--tumor tissues and their corresponding tumor-adjacent tissues." (PMID 29416786, 2018). "Stat1, STAT2, STAT3 and Tbet mRNA expression were tendencially upregulated in total lungs cells derived from αPD-1 antibody- treated tumor bearing mice independent from in vitro re-challenge." (PMID 30647851, 2018). "IFI27 is transcribed as a type I interferon (IFN-I) stimulated gene (ISG) mediated by the STAT1/STAT2/IRF9 complex, and activation of the interferon-alpha receptor and increased mRNA levels of ligands and receptors in the TGFB pathway play important roles in the PDAC tumor microenvironment." (PMID 41008826, 2025). "However, USP5 deficiency did not affect IFN-I response in tumor cells because neither p-STAT1 and p-STAT2 levels nor IFN-stimulated gene expression were changed in USP5-depleted cells." (PMID 41321309, 2025).
tumor (continued). "Together, these observations suggest that the tumor-promoting effects of STAT2 may operate in a tumor-cell intrinsic manner, rather than being driven by differences in IFNAR1-dependent immune signaling." (PMID 41440237, 2025). "STAT2-mediated initial IFN-I response drives the expression of antitumor IFN-stimulated gene factors that are pivotal in dendritic cell maturation, generation of killer CD8+ T cells, and recruitment of immune cells to the tumor site to restrict tumor growth and metastasis." (PMID 38611065, 2024). "As a result, the upregulation in expression of STAT2 mRNA was observed in KIRC patients compared to the normal healthy persons in the sub-group analyses based on sample types, race, gender, age, KIRC subtypes, tumor grade, cancer stages, and nodal metastasis status." (PMID 37115061, 2023). "Collectively, we show that the abundance of STAT2 and of USP18, in combination with information on patient‐specific IFNα levels allow us to propose with our calibrated mathematical model an IFNα treatment regime to prevent pathway desensitization and to optimize an antiviral or anti‐tumor response." (PMID 32696599, 2020). "Thus, the regulation of STAT2 might not have a significant impact on anti-tumour immunity." (PMID 35946310, 2022). "Our analyses showed that both tumor and nontumor cells expressed IFN signaling genes such as STAT1, STAT2, ISG15, OAS1, and MX1 in all three datasets." (PMID 34771447, 2021). "This is consistent with STAT2 being activated downstream of CD95 signaling, as our previous data also suggested that tumor cells cannot grow without CD95 expression." (PMID 31992798, 2020). "We find that high expression and T404 phosphorylation of STAT2 inhibit STING subcellular translocation and reduce the production of IRF3-dependent cytokines, including IFNs and T cell chemotaxis, without inhibiting IL-6 production, thus promoting tumor cell survival." (PMID 37036972, 2023).
cancer (78 papers, 2013 to 2026). A tumor composed of atypical neoplastic, often pleomorphic cells that invade other tissues. "Since STAT2 interacted with USP5 after IFN-β treatment and the phosphorylation-deficient STAT2 lost its binding potential, we then knocked out STAT2 in USP5-deficient cancer cells and found that it eliminated the secretion of p-STAT2 and p-STAT1." (PMID 41321309, 2025). "The top cancer genes with recurrent variants included: STAT2 (33%), DMNT1 (27%), HSP90AA1 (17%), CDK4, NOTCH2, THRAP3, and SALL4 (13% each)." (PMID 41353477, 2025). "The dysregulation of both STAT1 and STAT2 has been implicated in various types of cancer, including CRC." (PMID 39868645, 2025). "It is important to note that STAT2 expression, which we observed to be notably increased in our Sjögren’s disease cases, has also been implicated in cancer development." (PMID 38790257, 2024). "Taken together, our present results indicated that two anti-cancer drugs which induce cell death by different mechanisms, preferably kill highly differentiated STAT2-deficient tumoroids." (PMID 38001683, 2023). "Infiltration of resting memory CD4+ T cells and M1 macrophages positively associated with STAT2 expression; however, STAT2 negatively correlated with the infiltration of activated mast and memory B cells in most cancer types." (PMID 36176415, 2022). "Interestingly, Western blotting showed increased p-STAT1 and p-STAT2 levels in THP1-MΦ cocultured with IFN-β–treated USP5-deficient cancer cells." (PMID 41321309, 2025). "It is therefore conceivable that lowering STAT2 function, e.g., by dietary phytoestrogens, in poorly differentiated tumors, might render them more susceptible to killing by anti-cancer drugs." (PMID 38001683, 2023). "Also, several cancer-related kinases, miRNAs, and transcription factors associated with STAT2 were identified." (PMID 37115061, 2023). "The role of Signal Transducer and Activator of Transcription 2 (STAT2) in cancer remains poorly understood." (PMID 41440237, 2025). "In head-neck squamous cell carcinoma (HNSCC), STAT1, and STAT2 expression levels were significantly upregulated in tumors compared to normal tissues and positively correlated with individual cancer stage, grade, and nodal metastasis." (PMID 38191598, 2024). "Patients with cancers that express rich STAT2 have a more impaired prognosis than those expressing poor STAT2." (PMID 38474078, 2024). "Copy number amplification of the 10q24.32 locus in patients with advanced CRC leads to increased NFKB2 expression and its binding with STAT2, resulting in the activation of the PD‐L1/PD‐1 axis and immune escape by cancer cells." (PMID 38660687, 2024). "In the present study, both STAT1 and STAT2 are highly expressed and activated in LSCC, and associated with immune cell infiltration, suggesting their pro-cancer function and potential immune microenvironment remodeling functions." (PMID 38191598, 2024). "Cancer cells harboring the unphosphorylated STAT1/unphosphorylated STAT2/IRF9 complex are more resistant to DNA damage-inducing chemotherapy than those lacking the complex." (PMID 38474078, 2024). "The STAT2 signaling pathway, which plays a role in the immune response that includes cancer initiation and inflammation, was identified as a major upregulated pathway in response to doxycycline-induced BRD9 KD coupled with pomalidomide." (PMID 38610997, 2024). "Unphosphorylated STAT2 bridges the interferon-stimulated response and NF-κB elements in the IL-6 promoter and increases cancer cell survival by enhancing IL-6 expression." (PMID 38835896, 2024).
cancer (continued). "Our study reveals that Rg5 exerts anti‐cancer effects by reducing PD‐L1 expression through modulating the stability of the NFKB2/STAT2 protein complex." (PMID 38660687, 2024). "In the PDC000127 cohort, the protein expression level of STAT2 was higher in cancer tissue compared to normal tissue." (PMID 37600786, 2023). "Taken together, these experiments indicated that intestinal epithelial STAT2 can interfere with the actions of two different anti-cancer drugs which rely on different pathways to induce cell death." (PMID 38001683, 2023). "Mechanistically, nuclear USP18 controls the enhancer landscape of cancer cells and diminishes STAT2-mediated transcription complex binding to IFN-responsive elements." (PMID 36646704, 2023). "In parallel, we showed that both FOXA1 and ZBED2 play concordant roles in preventing inflammatory response in cancer cells through STAT2 inhibition." (PMID 36944729, 2023). "Our findings indicated that STAT2 exhibits a pathogenic contribution to the development of CRC and enhances the resistance to anti-cancer therapy." (PMID 38001683, 2023). "As expected, the majority of HN279 cancer cells expressed MDK, together with a number of genes associated with the pre-nodal phenotype (eg SNAI2, AXL, STAT2) that were unaffected by ICB." (PMID 36973261, 2023). "To confirm the direct binding of TF STAT2 and PD-L1 promoter, we also obtained STAT2 ChIP-seq profiles of multiple types of cancer cell lines, including GM12878, K562 and LoVo." (PMID 35946310, 2022). "We demonstrated that the overexpression of STAT2 can significantly upregulate PD-L1 expression in cancer cell lines DLD-1 and HeLa." (PMID 35946310, 2022). "The influence of CXCL10 and STAT2 expression on patient survival has been reported in several human cancers." (PMID 35207629, 2022). "Future studies should further validate the interaction of STAT2 and PD-L1 with larger data sizes, different cancer cell lines, and the STAT2 knockdown mouse model." (PMID 35946310, 2022). "We found that since STAT2 can upregulate PD-L1 expression on the surface of cancer cells, it can aid the cancer cells in escaping immunosurveillance." (PMID 35946310, 2022). "STAT3 and STAT2 belong to STAT family and are involved in STAT signaling, which are highly associated with TME and cancer progression." (PMID 35902970, 2022). "Since STAT2 can form a complex with IRF9 and induce the expression of ISGs in the absence of STAT1, which seems to be tissue‐ and context‐dependent, we next silenced STAT2 in CAF1 before adding the CM from treated cancer cells." (PMID 33476079, 2021). "Deeper understanding of the stimulation, action and degradation of STAT2 will assist efforts to treat the many cancers in which STAT2 activity is involved." (PMID 32973222, 2020). "The role of STAT2 in cancer is controversial; some reports implicate STAT2 in the carcinogenesis process, proposing that STAT2 can increase IL-6 secretion, and that this in turn activates STAT3, thus promoting tumorigenesis." (PMID 33076315, 2020). "The discovery of FBXW7 as a STAT2 stability regulator has deepened our understanding of the role of FBXW7 in human cancers." (PMID 32973222, 2020). "Yong-Yeon Cho and colleagues at The Catholic University of Korea in South Korea review the role of STAT2 in links between molecular signals of the immune response and the onset of cancer." (PMID 32973222, 2020). "The activity of STAT2, a protein stimulated by molecular signalling systems to activate selected genes in ways that can lead to cancer, is regulated by factors controlling its rate of degradation." (PMID 32973222, 2020). "It is important to point out that this is the first time that STAT2, NFE2L1, SIN3B and NOTCH2 genes are described associated to the cancer stroma." (PMID 31159827, 2019).